SLC30A10 (solute carrier family 30 member 10)
Diseases named in the same sentence as SLC30A10 in open-access papers (continued):
Sharing a sentence is not in itself a finding about the gene and the disease.
Cirrhosis (13 papers, 2012 to 2025). A chronic disorder of the liver in which liver tissue becomes scarred and is partially replaced by regenerative nodules and fibrotic tissue resulting in loss of liver function. "Loss-of-function mutations in SLC30A10 have previously been associated with cirrhosis, higher manganese levels in liver biopsy samples and neurotoxicity including parkinsonian-like movement disorders." (PMID 32247823, 2020). "SLC30A10 and SLC39A8 encode metal ion transporters and PNPLA3 and TM6SF2 are known genes associated with fatty liver and cirrhosis." (PMID 32247823, 2020). "SLC30A10 excretes manganese from the liver to the bile duct, and rare homozygous loss of function causes the syndrome hypermanganesemia with dystonia-1 (HMNDYT1) which involves cirrhosis." (PMID 34315874, 2021).
liver disease (11 papers, 2016 to 2025). "Recent genome-wide association studies revealed a link between the SLC30A10 variant T95I and markers of liver disease." (PMID 38336290, 2024). "Treatment with this chelator effectively reduces Mn accumulation, ameliorates neurological symptoms, and prevents liver disease progression in patients harboring SLC30A10 mutations." (PMID 36733764, 2022). "We identified novel associations between an MRI-derived measure of fibroinflammatory liver disease and variants in SLC30A10 and SLC39A8 that replicated with blood biomarkers of hepatocyte injury." (PMID 32247823, 2020). "Further studies will be needed to define whether other damaging missense variants or protein-truncating variants in SLC30A10, including the variants known to cause HMNDYT1, also predispose to liver disease in their heterozygous state." (PMID 34315874, 2021). "Future studies may determine whether targeting SLC30A10 and SLC39A8 are possible therapeutic options to prevent liver disease in at-risk individuals." (PMID 32247823, 2020). "However, unlike patients with a mutation in SLC30A10, these patients do not have increased hepatic Mn levels, nor do they develop liver disease." (PMID 28751976, 2017).
colorectal cancer (7 papers, 2014 to 2024). A primary or metastatic malignant neoplasm that affects the colon or rectum. "Among them, SLC30A10 is a known zinc binding protein imperative in autophagy and has been implicated in colorectal cancer." (PMID 25506832, 2014). "RNA sequencing data showed that SLC30A10 expression in colorectal cancer negatively correlates with its functional antagonists SLC39A14 and SLC39A8." (PMID 39596116, 2024). "Based on bioinformatics analysis of microarray expression data from the GEO database, SLC30A10 was previously identified as one of the top ten candidate genes marking colorectal cancer." (PMID 39596116, 2024). "Nevertheless, the data available through the COSMIC browser show that for a small group of colorectal cancer patients (~6%), there is increased expression of SLC30A10." (PMID 39596116, 2024). "Recently, the SLC30A10 gene was suggested as a promising methylation biomarker of colorectal cancer." (PMID 39596116, 2024). "SLC30A10 inhibits colorectal cancer progression and metastasis and can be used both as a prognostic biomarker and anti-metastatic therapeutic target." (PMID 34831349, 2021). "SLC30A10 is aberrantly expressed in colorectal cancer and is significantly related to the methylation epigenotype and molecular genesis of colorectal cancer." (PMID 33110097, 2020). "Importantly, the expression profile of SLC30A3 in colorectal cancer (downregulated in 92% of samples) correlates with SLC30A10." (PMID 39596116, 2024). "Low expression of SLC30A10 promotes cell proliferation and migration of colorectal cancer cells." (PMID 36293321, 2022). "Similarly, several reports suggested that SLC30A10 was a potential methylation biomarker for colorectal cancer 30-31." (PMID 35154468, 2022). "SLC30A10 has been observed to be downregulated in colorectal cancer tissues and cell lines." (PMID 36293321, 2022).
liver cirrhosis (7 papers, 2018 to 2025). "Fourth, SLC30A10 deficiency causes hypermanganesemia and liver cirrhosis in humans, and LOF variants are associated with MRI cT1, a marker of steatohepatitis and fibrosis." (PMID 40065360, 2025).
dystonia 1 (4 papers, 2019 to 2025). "Biallelic loss‐of‐function variants in the genes encoding the two Mn transporters, SLC30A10 and SLC39A14, cause autosomal recessive movement disorders termed hypermanganesemia with dystonia 1 (HMNDYT1) and 2 (HMNDYT2), respectively." (PMID 41177175, 2025).
Alzheimer disease (3 papers, 2013 to 2022). A progressive, neurodegenerative disease characterized by loss of function and death of nerve cells in several areas of the brain leading to loss of cognitive function such as memory and language. "Mutation and decreased SLC30A10 protein levels were discovered in the brain autopsy of Alzheimer’s Disease and PD patients." (PMID 36364894, 2022).
hypothyroidism (3 papers, 2017 to 2024). Abnormally low levels of thyroid hormone. "However, we are aware that at least one patient with SLC30A10 mutations has hypothyroidism (personal unpublished observations)." (PMID 31089831, 2019). "In SLC30A10 knockout mice, Mn accumulation in the thyroid gland also leads to pronounced hypothyroidism through Mn-induced inhibition of thyroxine production." (PMID 31089831, 2019). "It is important to note, however, that the severe hypothyroidism induced by Mn accumulation in Slc30a10-knockout mice differs from the symptoms present in patients with HMDPC." (PMID 28692648, 2017). "Additionally, knockout mice of Slc30a10 -/- showed high levels of Mn in the blood serum, hypothyroidism, a smaller size, and premature death compared to controls." (PMID 39064292, 2024).
prostate carcinoma (3 papers, 2022 to 2024). A carcinoma that arises from epithelial cells of the prostate gland. "Based on the Oncomine database records, the expression of Zn-exporter genes SLC30A1, SLC30A9, and SLC30A10 are upregulated, and SLC30A5 and SLC30A6 are downregulated in prostate cancer compared to BPH." (PMID 36551962, 2022).
Hepatic fibrosis (2 papers, 2025). The presence of excessive fibrous connective tissue in the liver.
Hypermagnesemia (2 papers, 2020 to 2025). An abnormally increased magnesium concentration in the blood. "It protects against Mn2+ toxicity in cells and mutations in Slc30a10 result in hypermagnesemia with dystonia 1 (HMNDYT1; OMIM: 613,280)." (PMID 39266724, 2025).
manganism (2 papers, 2014 to 2022). "Among all known Mn transporters, SLC30A10 appears to be a key regulator of Mn homeostasis, given that mutations in this genecan result in manganism in the absence of overexposure to this metal." (PMID 25136353, 2014).
schizophrenia (2 papers, 2016 to 2018). A major psychotic disorder characterized by abnormalities in the perception or expression of reality. "SNPs in SLC39A8 and SLC30A10 have previously been associated with neurological outcomes; SLC39A8 SNPs have been linked to schizophrenia, chronic stress, and mental disability, and SLC30A10 genotypes were associated with neurological performance in elderly people." (PMID 30619481, 2018).
acute cholecystitis (1 paper, 2021). "The top non-cancer hepatobiliary associations with SLC30A10 Thr95Ile were with K83.0, cholangitis; K83.1, obstruction of bile duct; and K81.0, acute cholecystitis." (PMID 34315874, 2021).
adenoma (1 paper, 2026). A neoplasm arising from the epithelium. "Downregulation of SLC30A10 in colorectal tubular adenoma is associated with manganese accumulation and alterations in the cGAS-STING pathway, suggesting its potential role in the development and progression of adenoma, a finding with promising research implications." (PMID 41991590, 2026).
bile duct cancer (1 paper, 2021). "The association of Thr95Ile with bile duct cancer led us to query expression of SLC30A10 in specific cell types within the liver using data from three single-cell RNA sequencing studies of liver." (PMID 34315874, 2021).
cervical cancer (1 paper, 2022). A primary or metastatic malignant neoplasm involving the cervix. "And a high expression of SLC30A1, SLC30A6, SLC30A8 and SLC30A10 was associated with worse overall survival in cervical carcinoma patients." (PMID 35154468, 2022). "Therefore, SLC30A1 and SLC30A10 can be used as potential diagnostic indicators and therapeutic targets in cervical carcinoma." (PMID 35154468, 2022). "Additionally, ROC curves were performed to evaluate the diagnostic effects of SLC30A1 and SLC30A10 in cervical carcinoma." (PMID 35154468, 2022). "Data in the UALCAN tool revealed that mRNA expressions of SLC30A1, SLC30A7 and SLC30A10 were significantly higher in cervical cancer tissues, while SLC30A2 and SLC30A8 mRNA levels were decreased compared to normal tissues." (PMID 35154468, 2022). "The results showed that the expression of SLC30A1 and SLC30A10 was elevated in cervical carcinoma tissues compared with paracancerous tissues." (PMID 35154468, 2022). "And we validated the expression of SLC30A1 and SLC30A10 in cervical carcinoma by performing immunohistochemical staining on 31 pairs of tissues." (PMID 35154468, 2022). "For metastases, we found that SLC30A1, SLC30A7 and SLC30A10 expression were positively correlated with lymph node metastasis or distant metastasis in cervical carcinoma." (PMID 35154468, 2022). "And we investigated the expression of SLC30A1 and SLC30A10 in cervical carcinoma by performing immunohistochemical staining on 31 pairs of tissues." (PMID 35154468, 2022). "In conclusion, we identified two genes (SLC30A1 and SLC30A10) that may play a promotional role in cervical cancer." (PMID 35154468, 2022). "Therefore, the correlation of SLC30A1 and SLC30A10 expression with immune cells and biomarkers in cervical cancer were investigated using the TISIDB platform." (PMID 35154468, 2022). "SLC30A1 and SLC30A10 can effectively distinguish cervical carcinoma patients, respectively." (PMID 35154468, 2022). "Besides, we found that SLC30A1, SLC30A7 and SLC30A10 expression was positively correlated with lymph node metastasis or distant metastasis in cervical carcinoma." (PMID 35154468, 2022). "However, after comprehensive integrative analyses of SLC30A1-10 genes in cervical carcinoma, we found that only two genes, SLC30A1 and SLC30A10, may potentially play a pro-cancerous role in cervical cancer." (PMID 35154468, 2022). "For immunostimulator, SLC30A10 expression was correlated with TNFRSF25 (Spearman: ρ = 0.202, P = 0.00038), TNFSF13 (Spearman: ρ = -0.193, P = 0.000703), TNFRSF13C (Spearman: ρ = -0.209, P = 0.000245), and RAET1E (Spearman: ρ = 0.197, P = 0.000546) in cervical carcinoma." (PMID 35154468, 2022). "For tumor stages, SLC30A1, SLC30A7 and SLC30A10 groups significantly varied, whereas SLC30A2, SLC30A3, SLC30A4, SLC30A5, SLC30A6, SLC30A8 and SLC30A9 did not significantly differ in cervical carcinoma." (PMID 35154468, 2022).
cholangiocarcinoma (1 paper, 2021). A carcinoma that arises from the intrahepatic biliary tree (intrahepatic cholangiocarcinoma) or from the junction, or adjacent to the junction, of the right and left hepatic ducts (hilar cholangiocarcinoma). "Because both SLC30A10 Thr95Ile and extrahepatic bile duct cancer are exceedingly rare, validation of this association in either another very large biobank or in a cohort of cholangiocarcinoma patients will be necessary." (PMID 34315874, 2021).
colon cancer (1 paper, 2022). "SLC10A2 (ASBT/Apical sodium-dependent bile acid transporter) and SLC30A10 (Solute Carrier Family 30 Member 10) are also downregulated in colon cancer." (PMID 36293321, 2022).
extrahepatic bile duct carcinoma (1 paper, 2021). A carcinoma that arises from epithelial cells of the extrahepatic bile duct. "The only phenome-wide significant associations of diagnoses with SLC30A10 Thr95Ile were C24.0, extrahepatic bile duct carcinoma, and C22.1, intrahepatic bile duct carcinoma." (PMID 34315874, 2021). "The association of SLC30A10 Thr95Ile with extrahepatic bile duct cancer was unexpected, as this disease has not been described in conjunction with HMNDYT1." (PMID 34315874, 2021).
GM1 gangliosidosis (1 paper, 2025). A rare lysosomal storage disorder characterized biochemically by deficient beta-galactosidase activity and clinically by a wide range of variable neurovisceral, ophthalmological and dysmorphic features. "While GM1 gangliosidosis and PLAN are relatively more common diseases, the total number of reported cases in the literature for SLC6A3, SLC30A10, and SLC39A14 is approximately 50 for each condition." (PMID 40362326, 2025).
hepatocellular carcinoma (1 paper, 2014). A malignant tumor that arises from hepatocytes. "The human SLC30A10 complements defective Mn2+ uptake in yeast cells lacking the Ca2+/Mn2+ ATPase PMR1 and the endogenous SLC30A10 expression increases with Mn2+ exposure in HepG2 hepatocellular carcinoma cells." (PMID 24904274, 2014).
Hyperammonemia (1 paper, 2023). An increased concentration of ammonia in the blood. "Collectively, our data establish a role of fructose in hepatic Mn and ammonia metabolism through ChREBP/Slc30a10 pathway, and postulate fructose dietary restriction for the prevention and treatment of hyperammonemia." (PMID 38040719, 2023). "Thus, we postulate that fructose overconsumption impairs hepatic Mn homeostasis and ammonia disposal through ChREBP/Slc30a10 pathway, and propose fructose dietary restriction for the prevention and treatment of hyperammonemia." (PMID 38040719, 2023).
hypermanganesemia with dystonia (1 paper, 2025). "Hypermanganesemia with dystonia 1 (HMNDYT1), resulting from bi-allelic mutations in SLC30A10, was the initial inherited defect in Mn transporters identified." (PMID 40278159, 2025).
Iron deficiency anemia (1 paper, 2021). "Consistent with hematological symptoms of hypermanganesemia, SLC30A10 Thr95Ile carriers have increased hematocrit and risk of iron deficiency anemia." (PMID 34315874, 2021).
liver failure (1 paper, 2024). A liver disease characterized by the liver losing or has lost all of its function. "The relevance of this finding certainly deserves future investigation, given that liver failure is one of the known consequences of SLC30A10 deficiency in patients." (PMID 38336290, 2024).
myopia (1 paper, 2012). "In addition, variations in the expression of murine gene ZC3H11A and two neighboring genes SLC30A10 and LYPLAL1 in the retina and sclera in a myopic mouse model implicate the role of these genes in myopia onset." (PMID 22685421, 2012).
oculogyric crisis (1 paper, 2025). A focal dystonia that is characterized by a prolonged involuntary upward deviation of the eyes. "While certain features like seizures or oculogyric crisis may be found in GLB1 and PTS, or SLC6A3 and SPR, respectively, levodopa response is more inconsistent in GLB1, SLC6A3, SLC30A10, and SLC39A14, and should guide the diagnosis." (PMID 40362326, 2025).
type 2 diabetes (1 paper, 2020). "cT1-increasing alleles at 4 variants (in SLC30A10, SLC39A8, TM6SF2, and PNPLA3) were associated with higher ALT and AST (all with p values <2×10−5) and higher risk of type 2 diabetes (all with p <0.002, except the SLC30A10 variant)." (PMID 32247823, 2020).
vitamin D deficiency (1 paper, 2022). A nutritional condition produced by a deficiency of VITAMIN D in the diet, insufficient production of vitamin D in the skin, inadequate absorption of vitamin D from the diet, or abnormal conversion of vitamin D to its bioactive metabolites. "Given the prevalence and widespread supplementation of vitamin D deficiency, it would be interesting to understand the physiological and pharmacological implications of vitamin D3 induction of SLC30A10/ZnT10." (PMID 36352900, 2022).
Zinc deficiency (1 paper, 2012). A deficiency of the essential metal Zinc; an essential cofactor for many enzymes. "It is possible that reduced expression of ATP13A2, which has been shown to reduce cellular manganese concentrations, occurs in response to severe zinc deficiency in our model, and a recent study revealed that ZnT10 (Slc30a10) plays a key role in manganese transport in humans." (PMID 22737083, 2012).
cancer (9 papers, 2019 to 2024). A tumor composed of atypical neoplastic, often pleomorphic cells that invade other tissues. "Hif1a is induced by hypoxia and ROS, and it would be interesting to investigate if SLC30A10 is induced in cancers by similar mechanisms." (PMID 35625809, 2022). "SLC30A10 is a zinc transporter maintaining zinc homeostasis, which when dysregulated can result in cancer initiation and progression." (PMID 34021172, 2021). "Taken together, these findings may suggest that the expression and methylation levels of the genes SLC30A10 and SLC30A3 may have predictive value for the sensitivity of cancer cells to platinum drugs, also inthe case of KRAS-mutated CRC cells." (PMID 39596116, 2024). "Two drugs (Neopeltolide and Tozasertib) can inhibit the high expression of SLC30A10 in cancers." (PMID 35154468, 2022). "In addition, the results showed that high expression of SLC30A1 was resistant to 79 drugs; two drugs (Neopeltolide and Tozasertib) can inhibit the high expression of SLC30A10 in cancers." (PMID 35154468, 2022). "In addition, the results showed that the high expression of SLC30A1 was resistant to 79 drugs or small molecules; Two drugs (Neopeltolide and Tozasertib) can inhibit the high expression of SLC30A10 in cancers." (PMID 35154468, 2022). "At the gene level, FDCSP (cancer cell migration and invasion), KIR2DL3 (immune response), SLC30A10 (antiapoptotic), MAB21L2, PCDH9 (cell adhesion), PEG3 (cell proliferation) were found to be highly expressed in the Lymph-node (LN)-positive samples." (PMID 37377901, 2023).
tumor (6 papers, 2016 to 2025). "The differential expression of SLC30A1, SLC30A5, SLC30A6, SLC30A9 and SLC30A10 was found to vary with tumor stage and grade and appears to be related mostly to early events in PCa development and progression." (PMID 27833104, 2016). "A prime example is SLC30A10, which has predominantly tumor suppressor activity." (PMID 41583444, 2025). "Methylated Solute Carrier Family 30 Member 10 (SLC30A10), claudin 1 CLDN1, and Inhibin Subunit Beta A (INHBA) were evidenced by SureSelectXT Methyl-Seq as being able to differentiate between normal and tumor tissue." (PMID 34638449, 2021). "SLC30A10 and GPNMB were both related to tumor-promoting inflammation and tumor progression." (PMID 38110638, 2023). "For tumor stages, SLC30A1, SLC30A7 and SLC30A10 groups significantly varied." (PMID 35154468, 2022).
genetic disorder (4 papers, 2017 to 2023). "In conclusion, we developed and functionally characterized two independent lines of slc30a10 mutant zebrafish and found that these models recapitulate the symptoms of patients with HMDPC, thereby providing an invaluable model for studying this genetic disorder." (PMID 28692648, 2017).
metabolic disorder (1 paper, 2024). "Herein, we describe the case of a 3-year-old boy with a rare metabolic disorder due to SLC30A10 bi-allelic mutations and characterized by hypermanganesemia, congenital erythrocytosis and neurodegeneration, also known as hypermanganesemia with dystonia 1 (HMNDYT1)." (PMID 38283630, 2024).